PMEPA1 (prostate transmembrane protein, androgen induced 1)
Diseases named in the same sentence as PMEPA1 in open-access papers (continued):
Sharing a sentence is not in itself a finding about the gene and the disease.
tumor (43 papers, 2008 to 2026). "New studies also indicate an upregulation of PMEPA1 in tumor-associated immune and stromal cells; however, its specific role in tumor stromal cells remains largely unexplored." (PMID 40649997, 2025). "KEGG assays revealed the genes associated with PMEPA1 expression were mainly enriched in several tumor-related pathways." (PMID 35497877, 2022). "It is also known as prostate transmembrane protein, androgen-induced 1 (PMEPA1) or solid tumor-associated gene 1 (STAG1)." (PMID 34638419, 2021). "PMEPA1 was first identified as being upregulated in renal cell carcinoma and was designated as solid tumor associated gene 1 (STAG1)." (PMID 32410997, 2020). "Higher PSA/PMEPA1 expression ratio significantly associated with multiple indicators of disease progression (tumor differentiation, margin status, extracapsular extension and seminal vesicle invasion." (PMID 25883222, 2015). "Hence, we focused on the cell cycle and tumor growth, investigating the underlying mechanisms of PMEPA1, potentially identifying it as a novel therapeutic target." (PMID 39607204, 2024). "The chi-squared test revealed that high PMEPA1 expression was significantly associated with a high tumor invasion depth, lymph node metastasis, vascular and neural invasion, a high TNM stage, and Ki67 positivity (P<0.05) but not with age, sex, or histological type (P>0.05)." (PMID 39607204, 2024). "The PMEPA1-a isoform bypasses the tumor-suppressive Hippo pathway by inhibiting LATS1/2 kinase activity." (PMID 41932868, 2026). "The increase in PMEPA1 expression was statistically significant in both tumor and mesenchymal cells, with more pronounced differences observed in mesenchymal cells: 24.43% of PC3 cells and 76.64% of MSCs exhibited increased expression." (PMID 40649997, 2025). "This gap in knowledge highlights the need for further investigation into the functional significance of PMEPA1 in MSCs and its potential implications in the tumor microenvironment modulation." (PMID 40649997, 2025). "Despite the observed increase in PMEPA1 mRNA levels in both tumor and stromal cells following 72 h of co-culture, we identified a decrease in the target protein levels." (PMID 40649997, 2025). "Previous research has indicated that the addition of TGF-β to the culture medium of tumor cells alters PMEPA1 expression within just two hours." (PMID 40649997, 2025). "In vitro knockdown of ALDH1A3 or associated genes such as FAM3C, MCC, PMEPA1, and IRS2 reduced tumor invasion, while in vivo reduction similarly curbed tumor growth and metastasis." (PMID 40781158, 2025). "As expression of PMEPA1 in androgen-independent tumor cells is primarily regulated by TGF-β, we have compared mRNA levels of TGF-β1, TGF-β2 and TGF-β3 in MSCs and PMEPA1-expressing MSCs." (PMID 40649997, 2025). "To assess the role of secreted factors from tumor cells in enhancing PMEPA1 expression levels, we performed experiments involving the transfer of conditioned media from tumor cells to mesenchymal stem cells, followed by a 24 h culture period." (PMID 40649997, 2025). "Immunohistochemical staining was subsequently performed on collected pathological slides, revealing greater PMEPA1 expression in tumor tissues than in adjacent normal tissues and significantly higher PMEPA1 staining scores in tumor tissues." (PMID 39607204, 2024). "Studies have reported that PMEPA1 plays a role in promoting tumor development in gastrointestinal tumors." (PMID 39607204, 2024). "The PMEPA1 overexpression group demonstrated faster tumor growth, as evidenced by the increased tumor size and weight, while the PMEPA1 knockdown group showed reduced tumor growth and weight." (PMID 39607204, 2024). "In vivo study showed that overexpressing PMEPA1 promoted tumor growth, while knocking down PMEPA1 inhibited tumor growth, as indicated by the level of the proliferation marker Ki67." (PMID 39607204, 2024).
tumor (continued). "In this study, we discovered that PMEPA1 promoted tumor progression, particularly by increasing tumor cell proliferation." (PMID 39607204, 2024). "Accumulating pieces of evidence have demonstrated that the PMEPA1 gene is a crucial regulator of tumor progression and multiple biological functions." (PMID 38173834, 2023). "Upregulation of a pseudo-EMT signature and of known Smad2,3 target genes such as Pmepa1 and Skil within the tumor cells is consistent with increased autocrine Activin-A signaling." (PMID 38304252, 2023). "Taken together, survival analysis further sheds light on the potential of PMEPA1 to be a novel biomarker in predicting tumor progression and prognosis." (PMID 38173834, 2023). "NF-κb signaling participated in PMEPA1-induced cell proliferation and tumor growth in immunodeficient mice." (PMID 38173834, 2023). "The overexpression of many other amplified genes (e.g., AURKA, HRH3, MIR646, MRGBP, PCK1, PMEPA1, SLCO4A1-AS1, SOX18, TNFRSF6B) is associated with PDAC cell proliferation and tumour growth." (PMID 36289850, 2022). "This suggests that PMEPA1 plays an important role in regulating tumor immunity, and therefore influences BLCA prognosis." (PMID 34777336, 2021). "In line with the previous results, PMEPA1 expression in BLCA tissues significantly correlated with marker genes expression from tumor-infiltrating monocytes, TAMs, DCs, Tregs, CAFs, MDSCs, and exhausted T cells." (PMID 34777336, 2021). "Next, we investigated the correlation between PMEPA1 expression and the status of tumor-infiltrating immune cells based on immune marker gene expression levels via the TIMER databases." (PMID 34777336, 2021). "Immunohistochemistry and survival analysis shed light on PMEPA1 potential to be a novel biomarker in predicting tumor progression and prognosis." (PMID 34777336, 2021). "And the expression analysis showed the PMEPA1 was mainly expressed in tumor cells and CAFs, TGFB1 was expressed in all three cells, and most of the chemokines were highly expressed in TAMs." (PMID 34777336, 2021). "The result shows that in tumor cells, PMEPA1 were negatively correlated with some chemokines (including CXCL1, CXCL11, CXCL2, CXCL8, CX3CL1) and positively correlated with CXCL14 and LAG3." (PMID 34777336, 2021). "The discrepancy of PMEPA1 expression status in various tumor context was likely the result of detection of different PMEPA1 gene isoforms and different hormone signaling mechanism involved." (PMID 32842649, 2020). "In this study, we first testified that PMEPA1 expresses higher in tumour than normal tissue in Gene Expression Omnibus database, in the Cancer Genome Atlas (TCGA) as well as in the clinical data we collected." (PMID 30887697, 2019). "The expression of PMEPA1 was higher in tumour budding cells than tumour parenchyma cells and normal epithelial cells." (PMID 30887697, 2019). "The continuous tumour volume measurement indicated the average of tumour volume of the PMEPA1‐overexpressed group is larger than the control group." (PMID 30887697, 2019). "SKIL and PMEPA1 mRNA expression in tumor tissues was significantly increased compared with controls and not correlated with protein levels in the blood of paired HCC patients." (PMID 28230858, 2017). "The observed enhanced resistance to AR inhibitors in response to PMEPA1 depletion was consistent with the observed castration resistance of PMEPA1shRNA harboring tumor xenografts." (PMID 25883222, 2015). "PMEPA1 represents a promising target for stromal cell intervention, given its low basal expression in normal cells and its significant upregulation within the tumor microenvironment." (PMID 40649997, 2025). "Its expression in mesenchymal stem cells, along with the modulation of its expression levels by tumor cells at short-term culture, suggests that the role of PMEPA1 in regulating the tumor microenvironment may be underestimated." (PMID 40649997, 2025).
tumor (continued). "Alteration of PMEPA1 level and its role in tumor progression still needs to be elucidated." (PMID 40649997, 2025). "Furthermore, the level of PMEPA1 mRNA was significantly elevated in MSCs cultured for 24 h with tumor cells compared to those maintained in a MSC monoculture (p < 0.05)." (PMID 40649997, 2025). "Notably, the co-culture of cells for 72 h resulted in a significant increase in PMEPA1 expression in both mesenchymal and tumor cells (p < 0.05)." (PMID 40649997, 2025). "In addition to tumor cells, PMEPA1 expression has been demonstrated for mesenchymal stem (MSCs), endothelial and immune cells." (PMID 40649997, 2025). "Expression levels of other activin A target genes, including Adam12, Pmepa1, and Lmcd1—known to be involved in receptor endocytosis, fibrogenesis, and tumor progression —were significantly elevated by activin A (confirming our previous studies), and entirely antagonized by NUCC-555." (PMID 38607090, 2024). "After tumor excision, Western blot analysis was performed, confirming PMEPA1 expression." (PMID 39607204, 2024). "Hence, we used RNA and TMA of our own patients and found that PMEPA1 was remarkably higher expressed in tumor tissues than in adjacent tissues, while METTL16 was negatively correlated with PMEPA1 expression." (PMID 38385084, 2024). "We found only PMEPA1 gene were noticeably over-expressed in tumor tissues and a poor prognosis." (PMID 38385084, 2024). "Similarly, in the GSE26899 dataset, PMEPA1 expression was higher in tumor tissues than in normal tissues." (PMID 39607204, 2024). "Extensive studies have confirmed that PMEPA1 is strongly correlated with the expression of markers and transcription factors associated with EMT, while EMT also influences the proliferation and migration of tumor cells." (PMID 38173834, 2023). "It remains to be further investigated whether the tumor-promoting effect of PMEPA1 is regulated by autophagy." (PMID 38173834, 2023). "PMEPA1 is involved in tumor immunity, suggesting PMEPA1 may be a potential immunotherapeutic target in CC." (PMID 35497877, 2022). "Moreover, PMEPA1 is a potential tumor suppressor in multiple myeloma (MM) and induces MM cell apoptosis by mediating c-Maf polyubiquitination and degradation but independently of the TGF-β signaling." (PMID 34777336, 2021). "This suggests that PMEPA1 plays an important role in regulating tumor immunity." (PMID 34777336, 2021). "In this regard, we examined if PMEPA1 overexpression could attenuate the tumor-suppressive effects of linc00941 siRNA on the KEYSE-510 cells." (PMID 34254950, 2021). "Likewise, PMEPA1 was positively correlated with the majority of tumor-infiltrating immune cells (TIICs) in BLCA." (PMID 34777336, 2021). "This provided further verification for the argument that, TGFbeta produced by CAFs, could induce PMEPA1 in tumor cells and CAFs, at the same time inhibit the expression of chemokine in tumor cells, CAFs and TAMs which thus inhibit the tumor immunity." (PMID 34777336, 2021). "Finally, this calls for further experiments using vivo models to explore the potential biological mechanisms of PMEPA1 in malignancy and tumor microenvironment (TME) of BLCA." (PMID 34777336, 2021). "Knockdown of PMEPA1 impaired lung metastasis and tumor growth of MDA-MB-231 cells." (PMID 34254950, 2021). "Moreover, PMEPA1 knockout is known to impair tumor growth, and THBS2 overexpression is known to be associated with vascular invasion, advanced primary tumor status and nodal metastasis." (PMID 34674656, 2021). "Moreover, the correlation analysis showed PMEPA1 were most strongly negatively correlated with chemokines in all three cells, and secondly correlated with part of chemokines in tumor cells and CAFs." (PMID 34777336, 2021). "Moreover, the PMEPA1 expression was positively correlated to tumor T-classification and grade in two datasets (Xiangya cohort and TCGA), which indicated the PMEPA1 can predict the progression of BLCA." (PMID 34777336, 2021).
tumor (continued). "More importantly, the high PMEPA1 level in tumour samples was correlated with the poor survival of CRC patients, which indicated that PMEPA1 could be considered as an independent prognostic marker." (PMID 30887697, 2019). "We then confirmed that mRNA expression of PMEPA1 was higher in tumour than normal tissue in TCGA and GEO database GDS2947 n = 32 P = 0.001, GSE31737 n = 40 P < 0.0001, GSE41329 n = 10 P = 0.0039, GSE32323 n = 17 P = 0.0002 and TCGA n = 32 P < 0.001, and all the data were from the paired samples." (PMID 30887697, 2019). "PMEPA1 knockdown accelerated the growth of CaP tumor cells in athymic nude mice." (PMID 25883222, 2015). "We have examined the impact of PMEPA1 depletion on tumor growth in vivo." (PMID 25883222, 2015). "Moreover, we evaluated the expression of genes that showed significant correlation with PMEPA1 in tumor cells, CAFs, and TAMs, which showed the PMEPA1 was mainly expressed in tumor cells and CAFs, TGFB1 was expressed in all three cells, and most of the chemokines were highly expressed in TAMs." (PMID 34777336, 2021). "Finally, Klf4 and Egr1 levels were lower in the CTCs containing Parsortix-isolated samples, while Dusp10 and Pmepa1 higher levels in these samples could indicate tumor presence." (PMID 35153760, 2021). "In consideration of the remarkably positive association between TGFB1 and PMEPA1, we could infer that the TGFbeta produced by the tumor cells, CAFs, and TAMs could induce PMEPA1 in tumor cells and CAFs and at the same time attract macrophages and inhibit T cells." (PMID 34777336, 2021). "To verify the PMEPA1 signature in BLCA, we focused on PMEPA1 expression, relationship with clinical parameters and immune cells in BLCA, and the IHC result in the Xiangya cohort showed that the macrophages (in the central tumor and peritumoral stroma) were strongly associated with PMEPA1 expression." (PMID 34777336, 2021). "As TGFβ likely regulates tumor progression via multiple genes/pathways, and PMEPA1 may only represent one of these genes, further studies are needed, especially in vivo, to delineate the functional contribution of PMEPA1 in HCC progression." (PMID 33608500, 2021). "In the female-specific panel, genes related to aberrant androgen signaling across tumor types like androgen receptor, PLXNA1, USP54, and PMEPA1 were influential." (PMID 42137503, 2026). "PMEPA1 upregulates the WNT pathway, metabolic pathways, and others, affecting tumor cell proliferation, migration, and survival." (PMID 40244296, 2025). "For instance, PMEPA1 (ENSG00000124225.15_3, log2FC = – 1.36, P = 0.036) displayed a positive correlation with inflammation from tumor-infiltrating immune cells." (PMID 38368363, 2024). "To summarize, PMEPA1 plays a central role in EMT-related signaling pathways and the TGF-β signaling pathway that promotes late tumor metastasis." (PMID 38173834, 2023). "PMEPA1 negatively regulates TGF-β/SMAD signaling, thereby suppressing its tumor-suppressive capacity." (PMID 37987362, 2023). "Studies based on bioinformatics analysis and in vitro assays showed that PMEPA1 played a role in bladder cancer (BLCA) progression and the tumor microenvironment (TME)." (PMID 38173834, 2023). "In particular, most of the amplified genes are involved in proliferation and tumour progression in PDAC, such as AURKA, HRH3, MIR646, MRGBP, PCK1, PMEPA1, SLCO4A1-AS1, SOX18, and TNFRSF6B." (PMID 36289850, 2022). "To further investigate the function of PMEPA1 in BLCA, we evaluated the correlation between PMEPA1 and TGFB1, chemokines, and immune checkpoints in tumor cells, CAFs, and TAMs." (PMID 34777336, 2021). "The results of single-cell mRNA sequencing show PMEPA1 were mainly expressed in basal tumor cells and CAFs, TGFB1 were mainly expressed in basal tumor cells, CAFs and TAMs, PTGS2 were hardly expressed in those cells." (PMID 34777336, 2021).
tumor (continued). "The results show PMEPA1 were mainly expressed in basal tumor cells, CAFs, endothelial cells, muscle cells, and urothelial cells, TGFB1 were mainly expressed in basal tumor cells, CAFs, and TAMs, PTGS2 were hardly expressed in those cells." (PMID 34777336, 2021). "GPNMB and CoL5A1 are the reported oncogenes; PMEPA1, POMT2, VGLL4 and SUMF1 show better survival and thus suggest tumor suppressive role are being regulated by EZH2 signifying its dual role." (PMID 30760814, 2019). "However, some studies showed PMEPA1 could inhibit tumour proliferation and metastasis." (PMID 30887697, 2019). "Additionally, cells with knocked down ALDH1A3 or the other key genes FAM3C, PMEPA1, and MCC showed reduced tumor xenograft growth and metastasis in mice, highlighting their role in tumor progression." (PMID 40781158, 2025). "Therefore, we selected a long-term co-culture model of tumor and stromal cells within a CSS to study PMEPA1 levels in MSCs." (PMID 40649997, 2025). "PMEPA1-overexpressing AGS cells, PMEPA1-silenced MKN-7 cells, and their respective control cells were subcutaneously injected into NOD-SCID mice to evaluate tumor growth." (PMID 39607204, 2024). "Although they were higher in tumor tissue than in normal colon, this was not so in tumors of mice with CTCs detected, where Pmepa1 mRNA levels were much lower than in healthy colon." (PMID 35153760, 2021). "In colorectal cancer cells, PMEPA1 gene induced EMT process via activating the bone morphogenetic proteins (BMP) signaling of TGF-β signaling network, and subsequently leading to accelerated proliferation and metastasis of tumor cell cells." (PMID 32842649, 2020). "Furthermore, we inoculated control and PMEPA1‐knockdown SW620 cell into male BALB/c nude mice, the continuous tumour volume measurement and the weight of the tumour indicated PMEPA1 knockdown reduces the proliferation in vivo." (PMID 30887697, 2019). "Notably, we did not observe a significant change in PMEPA1 levels in MSCs exposed to conditioned media from tumor cells, suggesting a potential role for autocrine regulation within MSCs, possibly involving TGF-β secreted by MSCs." (PMID 40649997, 2025). "Furthermore, overexpressing ALDH1A3 in ALDH1A3-negative PDAC cells (PANC-1/ALDH1A3OE) increased the expression of FAM3C, MCC, and PMEPA1, which was supported by our previous data demonstrating that ALDH1A3 overexpression in PANC-1 cells promoted tumor invasion in vitro." (PMID 40781158, 2025). "PMEPA1 expression was found to be independent of tumor grade and estrogen receptor status." (PMID 30760814, 2019). "PMEPA1 median centred ratio was related to recurrence in GSE38832, P = 0.03.We also testified the samples from Sir Run Run Shaw Hospital and found mRNA level of PMEPA1 expressed higher in the tumour than normal tissue and the higher expression is related to the poor prognosis." (PMID 30887697, 2019). "Furthermore, six tumor progression genes (GNAI2, ODC1, APP, TNFRSF12A, BASP1, and LARP6) and nine migration and metastasis‐related genes (MSN, FLOT1, LAMB3, MYL9, ITGB1, FTH1, TPM4, and PMEPA1), which could explain the invasive characteristics of SCC, were identified." (PMID 40776410, 2025). "PMEPA1, through a negative feedback loop, is described as the responsible to convert TGF-β from a tumor suppressor to a tumor promoter in breast cancer." (PMID 32410997, 2020).
prostate (4 papers, 2008 to 2023). "One of the aims of our study was to investigate the clinical and molecular characteristics roles of PMEPA1 isoforms and their expression ratios in prostate tumorigenesis." (PMID 32064040, 2020). "PMEPA1 gene manipulated biological activity and stability of both androgen and TGF-β signaling via its isoform specific functions in prostate tumorigenesis and disease progression." (PMID 32842649, 2020).